STXBP6 (syntaxin binding protein 6)
Description:
Forms non-fusogenic complexes with SNAP25 and STX1A and may thereby modulate the formation of functional SNARE complexes and exocytosis.
Synonyms: HSPC156; amisyn
Tractability: Antibody: UniProt places it where antibodies can reach, with high confidence. PROTAC: ubiquitination databases record sites on it; its protein half-life has been measured.
Gene: Protein-coding gene on chromosome 14 (24,809,454 to 25,050,333, reverse strand). Ensembl gene ENSG00000168952.
Subcellular location: Cytoplasm; Membrane
Gene Ontology:
Molecular function: cadherin binding involved in cell-cell adhesion
Biological process: SNARE complex assembly; negative regulation of exocytosis; cell-cell adhesion; regulation of SNARE complex assembly
Cellular component: adherens junction; cytoplasm; membrane
Genetic constraint (gnomAD): Loss-of-function variants: 21 observed, 27.04 expected, observed/expected ratio (o/e) 0.78, 90% interval 0.55 to 1.12. The upper end of that interval is the gene's LOEUF score, 1.12, which puts it in group 4 of 6, group 1 being the genes least tolerant of losing a copy. Missense variants: 232 observed, 266.14 expected, observed/expected ratio (o/e) 0.87, 90% interval 0.78 to 0.97. Synonymous variants: 97 observed, 97.24 expected, observed/expected ratio (o/e) 1, 90% interval 0.85 to 1.18.
Homologues: Orthologues: chimpanzee STXBP6 (100% identical), macaque STXBP6 (100% identical), dog STXBP6 (99% identical), guinea pig STXBP6 (99% identical), mouse Stxbp6 (99% identical), rabbit STXBP6 (99% identical), pig STXBP6 (96% identical), tropical clawed frog stxbp6 (81% identical), rat Stxbp6 (77% identical), zebrafish stxbp6 (74% identical), zebrafish stxbp6l (47% identical), Caenorhabditis elegans sec-3 (30% identical), and 1 more. Paralogues in human: EXOC1 (36% identical), EXOC1L (16% identical).
Diseases named in the same sentence as STXBP6 in open-access papers:
STXBP6 is named in the same sentence as 31 diseases in open-access papers, as found by Europe PMC text mining. Sharing a sentence is not in itself a finding about the gene and the disease. The quoted sentences say what the papers report.
autism (4 papers, 2011 to 2025). Persistent deficits in social interaction and communication and interaction as well as a markedly restricted repertoire of activity and interest as well as repetitive patterns of behavior. "The aberrant expression of STXBP6 is reported to be associated with multiple human diseases, including diabetes, autism, and cancers." (PMID 34722753, 2021). "STXBP6 (associated with childhood autism) may modulate synaptic function, and synaptic dysfunction plays an important role in neurodegenerative processes in PD." (PMID 40355913, 2025). "STXBP6 is associated with childhood autism, and its role in synaptic dysfunction may contribute to neurodegeneration in PD." (PMID 40355913, 2025). "Therefore, the STRING analysis revealed a robust interaction between the STXBP6 and SNAP25 genes, reinforcing the well-documented association of SNAP25 with autism." (PMID 38003627, 2023).
autism spectrum disorder (4 papers, 2021 to 2025). A spectrum of developmental disorders that includes autism, and Asperger syndrome. "Specifically, de novo mutations in STXBP6 have been linked to developmental epileptic encephalopathy and autism spectrum disorders, reinforcing its classification as a novel SNAREopathy gene." (PMID 40870030, 2025). "Ours is the first study to show evidence that a mutation in the STXBP6 gene correlates with a form of DEE as a comorbidity with autism spectrum disorder." (PMID 38256219, 2024). "The present whole exome sequencing (WES) study describes, for the first time, the occurrence of developmental epileptic encephalopathy and autism spectrum disorders as a result of a de novo deletion within the STXBP6 gene." (PMID 38003627, 2023). "STXBP6 is reported to be a brain-enriched SNARE protein and has been considered a candidate gene for autism spectrum disorder (ASD)." (PMID 33805317, 2021).
diabetes (3 papers, 2021). "STXBP6 has important roles in the development of multiple diseases, including neurological disorders, diabetes, and cancer in humans and animals." (PMID 34946969, 2021). "Some studies have indicated that Stxbp6 has important roles and is involved in the occurrence and development of many diseases, including neurological disorders, diabetes, and cancer." (PMID 33805317, 2021).
lung adenocarcinoma (3 papers, 2017 to 2025). A carcinoma that arises from the lung and is characterized by the presence of malignant glandular epithelial cells. "A previous study showed that STXBP6 overexpression inhibits the proliferation and motility and facilitates the apoptosis of lung adenocarcinoma cells, and low level of STXBP6 is associated with dismal prognosis of lung adenocarcinoma patients." (PMID 34722753, 2021). "Dual luciferase reporter assay demonstrated the presence of miR-582-3p in PC-9 lung adenocarcinoma cells in relation to STXBP6 and RGMB target binding." (PMID 40597380, 2025). "Our results provide a basis for the genetic etiology of lung adenocarcinoma by demonstrating the possible role of hypermethylation of STXBP6 in poor clinical outcomes in lung cancer patients." (PMID 28198450, 2017). "Therefore, in this study we explored the epigenetic inactivation of STXBP6 expression using lung adenocarcinoma patients." (PMID 28198450, 2017). "So far, we initially found the targeting relationship of PRKCQ-AS1/miR-582-3p regulatory axis and its target genes (STXBP6, RGMB) in lung adenocarcinoma cells." (PMID 40597380, 2025).
lung carcinoma (3 papers, 2017 to 2022). "Finally, lower expression of STXBP6 was found to be associated with poor clinical outcomes in lung cancer patients." (PMID 28198450, 2017). "Next, the role of STXBP6 in migration of lung cancer cell lines was investigated by transwell migration assays." (PMID 28198450, 2017). "Since STXBP6 was epigenetically down-regulated in lung cancer cells, we investigated the functional roles of STXBP6 by transiently transfecting a STXBP6 expression plasmid into A549 and H1299 cells." (PMID 28198450, 2017). "Ectopic expression of STXBP6 resulted in slower cell proliferation, less colony formation, slower migration ability, and a greater percentage of apoptosis in lung cancer cells." (PMID 28198450, 2017). "After successfully overexpressing STXBP6 in lung cancer cells, we first examined the effect of STXBP6 on cell growth by MTT assays." (PMID 28198450, 2017). "Fourth, functional analysis revealed that STXBP6 suppressed tumor growth in lung cancer cell lines." (PMID 28198450, 2017).
rheumatoid arthritis (3 papers, 2012 to 2022). A chronic, systemic autoimmune disorder characterized by inflammation in the synovial membranes and articular surfaces. "The STXBP6 gene provides a syntoxin-binding protein which attaches to the SNARE complex components, preventing membrane fusions such as phagocytosis, and the STXBP6 gene causes rheumatoid arthritis." (PMID 36230283, 2022). "Variation of STXBP6 might affect the response of TNF-α inhibitors in rheumatoid arthritis patients." (PMID 32296631, 2020).
breast carcinoma (2 papers, 2018 to 2025). "In the in vitro model of breast cancer progression used in that study, STXBP6 was hypermethylated and downregulated in the transformed cells compared to the parental MCF-10F cells." (PMID 30286088, 2018). "To date, STXBP6 has not been reported in human cancer except in breast cancer cell transformation." (PMID 30286088, 2018).
developmental epileptic encephalopathy (2 papers, 2023 to 2025). "Our research aimed to elucidate a plausible, robust correlation between STXBP6 gene deletion and the manifestation of developmental epileptic encephalopathy." (PMID 38003627, 2023). "In conclusion, our study presents a novel and compelling case of developmental epileptic encephalopathy and ASD resulting from a de novo deletion within the STXBP6 gene, responsible for encoding the pivotal syntaxin-binding protein 6 (STXBP6), also known as amysin." (PMID 38003627, 2023).
COVID-19 (1 paper, 2025). A disease caused by infection with severe acute respiratory syndrome coronavirus 2. "Among the 5 common DEGs, four were significantly downregulated (ERP27, SYTL5, EXTL1, DIO2) and one was upregulated (STXBP6) in the COVID-19 dataset." (PMID 40660393, 2025). "Given that STXBP6 was located at the core of the PPI network and was uniquely upregulated in both the pterygium and COVID-19 datasets, we conducted siRNA-mediated knockdown in HConFs to investigate its potential role." (PMID 40660393, 2025).
epilepsy (1 paper, 2024). A brain disorder characterized by episodes of abnormally increased neuronal discharge resulting in transient episodes of sensory or motor neurological dysfunction, or psychic dysfunction. "Another undeniable advantage of using WES is the possibility of identifying new possible candidate genes; the present study led to the identification of three genes never before related to epilepsy, namely, KCNC2, STXBP6 and DHRS9." (PMID 38256219, 2024).
glioma (1 paper, 2014). A benign or malignant brain and spinal cord tumor that arises from glial cells (astrocytes, oligodendrocytes, ependymal cells). "In another study, STXBP6 (syntaxin binding protein 6-amisyn) that is known to be involved in vesicle-mediated intracellular transport was found to be differentially expressed in high versus low grade gliomas." (PMID 25026297, 2014).
hepatocellular carcinoma (1 paper, 2025). A malignant tumor that arises from hepatocytes. "With its level of expression elevated in hepatocellular carcinoma, STXBP6 was reported to have a regulatory role in the expression of PD-L1 in tumor cells." (PMID 40660393, 2025).
insulinoma (1 paper, 2021). "Down-regulation of Stxbp6 can stimulate glucose-induced growth hormone release in INS-1 832/13 rat insulinoma cells." (PMID 33805317, 2021). "Overexpression of Stxbp6 can suppress hormone release in INS-1 832/13 rat insulinoma cells and human β-cell line EndoC-βH2." (PMID 33805317, 2021).
Parkinson’s disease dementia (1 paper, 2025). "STXBP6 has been identified as a synaptic vesicle release regulator and potential biomarker in Parkinson’s disease dementia, implicating its role in movement execution and memory integration." (PMID 40870030, 2025).
psoriasis (1 paper, 2011). An autoimmune condition characterized by red, well-delineated plaques with silvery scales that are usually on the extensor surfaces and scalp. "In all five mouse phenotypes, there was increased expression of S100a9, Lcn2, S100a8, Sprr1b, Mpzl2, Has3, as well as decreased expression of Tppp, Stxbp6, and Cldn23, and each of these effects is consistent with characteristic expression patterns in clinical psoriasis." (PMID 21483750, 2011).
pterygium (1 paper, 2025). A wedge-shaped fibrovascular lesion arising from the bulbar conjunctiva and extending to the cornea. "A similar tendency was observed in pterygium tissues versus normal controls, with a significant decrease in the level of four genes (ERP27, SYTL5, EXTL1, DIO2) and an increment of gene STXBP6." (PMID 40660393, 2025).
scleroderma (1 paper, 2022). Scleroderma is a rare autoimmune connective tissue disorder characterized by abnormal hardening of the skin and, sometimes, other organs. "Transcripts of STXBP6 were also found to be among eight of other genes that were correlated with the modified Rodnan skin thickness score and forced vital capacity in humans suffering from scleroderma and systemic sclerosis, a condition that is characterized by thickening and hardening of the skin." (PMID 35227193, 2022).
cancer (6 papers, 2017 to 2022). A tumor composed of atypical neoplastic, often pleomorphic cells that invade other tissues. "With this approach, we identified STXBP6, whose expression was significantly repressed by methylation, affected cellular function in cancer cell lines, and was associated with overall survival." (PMID 28198450, 2017). "A nother recent study showed that the expression level of STXBP6 predicted the response to PD-1/PD-L1 immunotherapy in patients with cancer." (PMID 36698420, 2022).
tumor (5 papers, 2017 to 2025). "The results showed that circ_0002346 overexpression markedly restrained xenograft tumor growth in vivo, and its tumor suppressor role was at least partly based on the regulation of the miR-582-3p/STXBP6 axis." (PMID 34722753, 2021). "STXBP6 protein expression was downregulated in 91.43% of tumor tissues, BCL6B was downregulated in 88.57%, FZD10 was downregulated in 88.57%, and HSPB6 was downregulated in 91.43% (p <0.001, the original blots of western blots is shown in the S1–S8 Figs)." (PMID 30286088, 2018). "STXBP6 mRNA expression was downregulated in 66.67% of tumor tissues, BCL6B was downregulated in 69.23%, FZD10 was downregulated in 71.79%, and HSPB6 was downregulated in 74.36% (p <0.001)." (PMID 30286088, 2018). "Third, pyrosequencing and 5-aza-2′-deoxycytidine treatment showed the regulatory role of methylation of STXBP6 in tumor cells." (PMID 28198450, 2017). "In addition, we found that the staining intensity of STXBP6 was markedly increased in circ_0002346-overexpressed tumor tissue in comparison with the lenti-NC group." (PMID 34722753, 2021). "Moreover, we measured the expression of the circ_0002346/miR-582-3p/STXBP6 axis in tumor tissues." (PMID 34722753, 2021). "Furthermore, in tumor cells alone, 5-aza-2′-deoxycytidine treatment increased the expression levels of STXBP6 in a dose dependent manner and pyrosequencing showed higher percentage of methylation in STXBP6 promoter." (PMID 28198450, 2017). "The methylation and expression validation results identified 4 candidate genes (STXBP6, BCL6B, FZD10, and HSPB6) that were significantly hypermethylated and downregulated in most of the tumor tissues compared with the noncancerous lung tissues." (PMID 30286088, 2018).
neurological disorders (2 papers, 2021). "Next, we performed a series of behavioral tests on Stxbp6-null mice to assess whether they have neurological disorder phenotypes." (PMID 33805317, 2021). "Together, these findings suggest that Stxbp6 has important biological functions, though its depletion may be insufficient to induce severe neurological disorders, at least in our experimental setting." (PMID 33805317, 2021).
STXBP6 also shares sentences with these, for which no sentence is quoted: adenocarcinoma (1 paper); cognitive decline (1); coloboma (1); colon cancer (1); lymph node metastasis (1); neurodegenerative disease (1); non-small cell lung carcinoma (1); Obesity (1); Pick’s disease (1); rectal cancer (1); systemic sclerosis (1).